IFITM3 (interferon induced transmembrane protein 3)
Diseases named in the same sentence as IFITM3 in open-access papers (continued):
Sharing a sentence is not in itself a finding about the gene and the disease.
tumor (continued). "However, validation of these findings in tissues from COAD patients using the RT–qPCR showed that IFITM3, but not IFITM1, was highly expressed in the tumor, which indicated the positive association of IFITM3 expression with the disease progression." (PMID 38167862, 2024). "Moreover, exosomal S100A11 activated IFITM3/Akt passway in tumour cells." (PMID 39756316, 2024). "However, it remains to be further clarified whether IFITM3 is merely a biomarker for tumor immunogenicity or has a regulatory effect on antitumor immunity." (PMID 34456915, 2021). "Moreover, the intracranial implantation of BTPCs transduced with lentiviruses encoding for IFITM3-specific shRNAs or shScr control into immunocompromised mice gave rise to tumors of comparable sizes and did not alter the overall survival of tumor-bearing mice." (PMID 27835870, 2016). "However, some studies indicated IFITM3 plays an important role in inhibiting tumor development." (PMID 24370119, 2013). "Our study demonstrated that IFITM3 upregulates MHC-I expression and enhances tumor sensitivity to PD-1 inhibitors in SCLC patients by promoting CD8 + T cell infiltration and cytotoxic." (PMID 40611157, 2025). "In the present study, we report a GSCs-mediated angiogenesis manner, in which IFITM3 expressed in GSCs regulates JAK/STAT3 signaling pathway that preferentially stimulates bFGF production, leading to tumor angiogenesis." (PMID 38218875, 2024). "IFITM3 is frequently overexpressed in various tumor tissues, exhibiting the highest expression levels among the IFITM family in both normal and tumor tissues." (PMID 39459876, 2024). "On the contrary, knocking out both IFITM3 and STAT1 in TI-Tregs restores the suppression function and inhibits the anti-tumor response." (PMID 38167862, 2024). "Disrupting this circuit genetically, either by knocking out IFITM3 or STAT1, has therapeutic efficacy in tumor models by abolishing the function of TI-Tregs." (PMID 38167862, 2024). "Our data defines IFITM3-mediated Treg suppression function in a mice tumor model and highlights the correlation between STAT1 and IFITM3 regulation in TI-Treg cells." (PMID 38167862, 2024). "From our data, IFITM3 suppresses the transcription function and protein stability of STAT1 to maintain Treg function in the tumor microenvironment." (PMID 38167862, 2024). "On the other hand, those spots within the tumor parenchyma expressed more tumor cell genes (e.g., PMEL) and IFN-stimulated genes (e.g., ISG15, IFITM3, IFI6), confirming their closeness to tumor cells and IFN activation." (PMID 37655659, 2023). "IFITM3 expression is reduced by Krüppel-like factor 4 (KLF4), a known tumor suppressor that interacts with β-catenin and thus inhibits Wnt/β-catenin signaling in the human intestinal epithelium." (PMID 36466909, 2022). "Although IFITM2 is less frequently mentioned in tumor-focused studies, this protein seems to act in a similar manner to IFITM1 and IFITM3." (PMID 36466909, 2022). "In our study, it was found that the expression of IFITM3 in HCC was significantly increased, and its expression was related to the prognosis of HCC, and it was also closely related to TNM staging and tumor venous infiltration." (PMID 34659578, 2021). "Several genes of antiviral immune response pathways such as HLA-B, HLA-C, HLA-DQB1 IFI6, IFITM3, CD74, and tumor suppressor genes EFEMP1 and EGR1, are upregulated in tumor and downregulated in TAS." (PMID 34316327, 2021). "The results of this study support the previous studies that have shown IFITM3 is overexpressed in HCC and the overexpression of IFITM3 is significantly correlated with tumor metastasis and proliferation in HCC." (PMID 33816616, 2021). "In the IMvigor210 cohort, IFITM3 exhibited the highest expression in IC2 (immune cells with the highest PD-L1 values), TC2 (tumor cells with the highest PD-L1 values), and the inflamed phenotype." (PMID 34456915, 2021).
tumor (continued). "Compared with the low-IFITM3 group, the high-IFITM3 group exhibited a higher ESTIMATE Score, Immune Score, and Stromal Score but lower tumor purity, indicating that tumors with high IFITM3 expression were accompanied by increased immune cell infiltration." (PMID 34456915, 2021). "Interferon-induced transmembrane protein 3 (IFITM3) protein expression was expressed in the cytoplasm of metastatic lung adenocarcinoma tumor tissues and was correlated with higher tumor grade." (PMID 35008645, 2021). "HERC2P8 is pseudogene with no know biological function, while IFITM3 is a gene that has been shown to modulate the tumor microenvironment by promoting T cell infiltration, which is essential for antitumor immunity." (PMID 41541690, 2026). "Differential expression analysis of these 27 intersecting genes in the GSE87211 dataset from GEO revealed significant expression differences between tumor and normal groups for 26 genes, with ASCL2, IFITM3, IFITM1, SMPDL3A, and SUCLG2 being the five most significantly differentially expressed." (PMID 41595533, 2026). "In line with the observations from the IFITM3 overexpression studies, EG treatment alone did not significantly inhibit tumor growth in nude mice." (PMID 40611157, 2025). "Mmp7 and Ifitm3 are known to promote metastasis in human CRC, and Ccl9 expression by epithelial cells promotes tumor invasion through recruitment of Ccr1+ myeloid cells to the tumor’s invasive front in a mouse model of CRC." (PMID 41384492, 2025). "IFNγ could induce the expression of IFITM3 and STAT1, and the IFITM3 cKO mice showed higher IFNγ expression in the tumor environment to mediate a more robust anti-tumor response." (PMID 38167862, 2024). "Surprisingly, it revealed that IFITM3 expression was only significantly related to tumor grade, rather than gender, age and tumor size." (PMID 38218875, 2024). "Our research aimed at the immune cell, hence we further evaluated the expression of IFITM3 in nonimmune and tumor cells based on the 10 single-cell datasets in the TISCH database." (PMID 37304304, 2023). "Furthermore, in general, IFITM3 is expressed at the highest level, and IFITM2 is expressed at the lowest level in normal and tumor tissues (the GTEx Portal)." (PMID 36466909, 2022). "In contrast to IFITM3, IFITM1 and IFITM2 are less frequently assessed in tumor-focused studies." (PMID 36466909, 2022). "The results showed significantly higher IFITM3 expression in the tumor parts than the non-tumor regions." (PMID 35941699, 2022). "Moreover, we demonstrated ectopic expression of IFITM3 suppressed FOXO3 expression, consequently led to c-MYC induction to promote tumor growth, cell metastasis, cancer stemness as well as chemoresistance." (PMID 35941699, 2022). "To further correlate clinical significance of IFITM3, we carried out immunohistochemistry (IHC) staining analyses on tumor (n = 122) and non-tumor (n = 107) regions from the GC specimens." (PMID 35941699, 2022). "In addition, IFITM3’s role in shaping innate and adaptive immune responses demonstrates a wider role in the TME and in the fine balancing of tumor immune responses and inflammation." (PMID 33364194, 2020). "Again, the silenced expression of IFITM3 did alter neither MG infiltration into the tumor nor blood vessel neoangiogenesis." (PMID 27835870, 2016). "Immunostainings of tumor biopsies confirmed that radio-selection did not induce the expression of IFITM3 in GL261 cells." (PMID 27835870, 2016). "Along this line, the overall survival of tumor-bearing mice was not altered by the ectopic expression of IFITM3." (PMID 27835870, 2016). "Based on in vivo data presented above, modulation of IFITM3 did not affect tumor growth and progression in BTPC xenografts." (PMID 27835870, 2016). "Data suggest that tumor neoangiogenesis in BTPC xenografts was not affected by the ectopic expression of IFITM3-myc." (PMID 27835870, 2016).
tumor (continued). "Putatively, ectopic IFITM3-myc expression did not affect tumor cell properties to a significant extent as 1080 cells already expressed a significant amount of endogenous IFITM3." (PMID 27835870, 2016). "Data suggest IFITM3 did neither affect tumor growth in a BTPC mouse xenograft nor render the cells resistant to IR." (PMID 27835870, 2016). "For example, the downregulation of Onecut1 and upregulation of Ifitm3 might inhibit cell proliferation, whereas the downregulation of GADD45G might enhance tumor cell growth." (PMID 18307821, 2008). "Macrophage in this cluster had high expression of type I interferon signaling related genes (IFITM3, IFI27, MX1, IFI6, and ISG15) as well as gene features related to immunosuppressive phenotype (APOE, APOC1, S100A9, and GPNMB), whereby participating in tumor immune regulation." (PMID 35265520, 2022). "Here, we provide a summary of the current knowledge on the roles of the IFITM1, IFITM2 and IFITM3 proteins in different types of tumors and the molecular mechanism, effect on anticancer therapy and links between IFITM-interacting partners with an overlap with tumor progression." (PMID 36466909, 2022). "Thus, IFITM3 is also an important factor for tumor metastasis in several cancers, but we did not observe any upregulation of IFITM3 in metastatic sites in the orthotopic SCLC metastasis model (data not shown)." (PMID 32668617, 2020). "Furthermore, gain and loss of function studies using BTPCs ectopically expressing IFITM3 or having IFITM3 down-modulated by a shRNA approach, did affect neither tumor growth nor animal survival." (PMID 27835870, 2016). "However, the relationship between IFITM3 and the landscape of tumor immunity has not been explored." (PMID 34456915, 2021). "The role of IFITM3 in tumor immunity is not well described but cellular distributions may clarify whether IFITM3 is tumorigenic, or merely part of a reaction to cytokines in the TME, and whether IFITM3 overexpression occurs only in transformed cancer cells or in stromal cells or both." (PMID 33364194, 2020). "Therefore, we wondered whether or not the ectopic expression of IFITM3 may affect tumor formation or progression." (PMID 27835870, 2016). "Therefore, it was investigated whether or not the tumor vasculature was altered in BTPC xenografts upon ectopic IFITM3 expression." (PMID 27835870, 2016). "Here, we identified a negative feedback loop in which reduced IFITM3 expression induces higher phosphorylation of STAT1, which promotes IFNγ responses in tumor-infiltrating Treg cells (TI-Tregs) and induces the fragility of TI-Tregs." (PMID 38167862, 2024). "Secondly, since the role of IFITM3 in SKCM was not clear, more real-world studies enrolling more tumor specimens and more experiments in vitro or in vivo should be performed in the future to reveal its actual function." (PMID 37304304, 2023). "Lastly, the vasculature and the extent of microglia/macrophage invasion into the tumor were studied in BTPC and GL261 tumors but neither parameter was altered by IFITM3." (PMID 27835870, 2016). "Collectively, these results suggest that the absence of IFITM3 in Treg cells contributes to the infiltration of tumor-killing cells and the production of effector cytokines in the TME, leading to a more robust anti-tumor response." (PMID 38167862, 2024). "We found that in the absence of IFITM3, phosphorylation of P38-AMPK was significantly weakened and the phosphorylation level of CDK1 (CDC2) was also decreased, confirming the effect of IFITM3 on tumor cell proliferation." (PMID 31273201, 2019). "Thus, targeting inhibition of IFITM3 and breaking this negative feedback loop for IFN-γ-mediated antitumor immunosuppression could be an option to modulate the tumor immune microenvironment in gastrointestinal tumors for therapies." (PMID 40909948, 2025).
cancer (61 papers, 2013 to 2026). A tumor composed of atypical neoplastic, often pleomorphic cells that invade other tissues. "IFITM3, a two-transmembrane-type protein that is closely associated with tumors, is strongly expressed in cancer." (PMID 38239300, 2024). "On the other hand, in vitro studies often describe that targeted IFITM1, IFITM2 and IFITM3 protein silencing in cancer cells causes proliferation inhibition, cell cycle arrest and senescence." (PMID 36466909, 2022). "Over the last few decades, IFITM3 has been identified as a functional gene in multiple human cancers, indirectly affecting ongoing inflammation and immune and cancer epithelial-to-mesenchymal transition (EMT)-associated pathways." (PMID 34456915, 2021). "Interferon (INF)-induced transmembrane protein 3 (IFITM3), a highly expressed transmembrane protein in cancer cells, is believed to be associated with metastasis in various cancers, e.g., acute myeloid leukemia, hepatomas, and gliomas." (PMID 32443915, 2020). "IFITM3 has also been functionally implicated in this cancer type, as its knockdown suppressed tumor cell migration, invasion and proliferation capacity." (PMID 29162141, 2017). "It remains unclear whether IFITM3 overexpression occurs solely in transformed cancer cells, matrix cells, or both, and the underlying mechanism remains elusive." (PMID 39459876, 2024). "We further analyzed the mutation status of ACE2, TMPRSS2 and IFITM3 in pan-cancers." (PMID 33061814, 2020). "Recently, IFITM3 has also been identified as a potent biomarker for predicting immunotherapy efficacy in some cancers and its overexpression has been shown to enhance antitumor immunity." (PMID 41541690, 2026). "Its contribution was further reinforced by suppression interactions involving DSTN and IFITM3, highlighting its functional embedding within cancer-specific metabolic networks." (PMID 40941703, 2025). "Recently, interferon-induced transmembrane protein-3 (IFITM3), a membrane protein associated with inflamed phenotypes and cancer, has been identified as a key vector of paracrine transmission of senescence from senescent cells to nearby parenchymal cells." (PMID 40348745, 2025). "COX-2, WBP2, IFITM3, and SFRP4 are associated with cell proliferation and inflammation in a variety of cancers." (PMID 38239300, 2024). "The ability of IFITM3 to confer spheroid-forming upon various cancers suggests its potential role in the maintenance of cancer stem cells." (PMID 39459876, 2024). "IFITMs, especially IFITM3, have been shown to play multifaceted roles in regulating the various signaling pathways involved in both adaptive immunity and cancer development." (PMID 38793616, 2024). "The proliferation, invasion, and migration of cancer cells can be significantly inhibited after silencing IFITM3." (PMID 38239300, 2024). "While GSCs were enriched for IFITM3, GSC serum-differentiated cells (GSDCs) exhibited reduced expression, indicating that IFITM3 was solely expressed in neural stem cells or cancer stem cells." (PMID 38218875, 2024). "Krüppel-like factor 4 (KLF4) is a common downregulated TF in cancer that would inhibit IFITM3 and SOX4 expression." (PMID 39228892, 2024). "IFITM3 is a well-studied gene in multiple diseases, and has close relation to cancers because it overexpresses in various types." (PMID 37304304, 2023). "A poor prognosis has been related to the expression of the IFITM1, IFITM2, or IFITM3 proteins in a number of cancers, including colorectal, prostate, ovarian, lung, liver, breast, and astrocytomas." (PMID 37353775, 2023). "The protein expression of IFITM1, IFITM2, or IFITM3 are predictors for poor prognosis in numerous cancers such as colorectal, prostate, ovarian, lung, liver, breast, and astrocytoma." (PMID 36435199, 2023). "In order to explore the impact of IFITM3 on cancer stemness, we then enriched CSCs from both TMK-1 and AGS stable cell lines overexpressing IFITM3 in stem-cell-selective conditions." (PMID 35941699, 2022).
cancer (continued). "Overexpression of IFITM3 has been shown to increase cancer hallmarks like cell proliferation, epithelial–mesenchymal transition and invasion." (PMID 36153346, 2022). "For some pathologies, inhibition of IFITM3 will be beneficial (cancer conditions), whereas for other conditions, such as inhibition of viral entry, the activation of IFITM3 can be useful." (PMID 36153346, 2022). "Several studies have postulated that high expression of the IFN-stimulated IFITM1 and IFITM3 proteins can stimulate more aggressive growth of human cancers." (PMID 36008984, 2022). "To date, IFITM1, IFITM2 and IFITM3 overexpression has been described in various cancer cell lines and tissues." (PMID 36466909, 2022). "IFITM3 expression is found to be upregulated in several cancers including breast cancer, prostate cancer, colon cancer, lung cancer, gastric cancer." (PMID 36153346, 2022). "IFITM3, interferon-induced transmembrane protein, plays a key role in cancer cell growth and maintenance, and is a marker of poor prognosis with high expression in many cancers, including AML." (PMID 35186733, 2022). "In present study, we unraveled IFITM3 for the first time as a critical mediator that promotes chemoresistance by elevating cancer stemness of GC." (PMID 35941699, 2022). "IFI27, CRYM, HBD, and IFITM3 in TEPs were positively related to the pan‐cancer stage and essential for diagnosing cancers with a sensitivity of 59.1%, 57.8%, 54.3%, and 60.9%, and a specificity of 90.9%, 89.1%, 72.7%, and 94.5%, respectively." (PMID 33955587, 2021). "We found that most types of cancer expressed higher IFITM3 than normal tissues, which was in accordance with previous reports." (PMID 34456915, 2021). "Interferon-induced transmembrane protein 3 (IFITM3) is an interferon-induced membrane protein, which has been identified as a functional gene in multiple human cancers." (PMID 34456915, 2021). "On the other hand, HBV expression correlated negatively to IFITM3 expression, a classical antiviral interferon stimulated gene suggesting an interplay with the virus and cancer cell innate immune responses." (PMID 34290079, 2021). "The results revealed that IFITM3 exhibited positive correlations with a majority of immunomodulators in almost all cancer types." (PMID 34456915, 2021). "Collectively, these results reveal the potential of IFITM3 as an immune-related biomarker in human cancers, especially BLCA." (PMID 34456915, 2021). "The results showed that IFITM3 was positively correlated with the T-cell inflamed score in most cancers except for TGCT, MESO, CHOL, and READ." (PMID 34456915, 2021). "IFITM3 protein expression was higher in cancer tissues in comparison with adjacent normal hepatic tissues." (PMID 33816616, 2021). "The role of IFITM3 in cancer has been preliminarily summarized, but its relationship to antitumor immunity is still unclear." (PMID 34456915, 2021). "We found that there were three cancer types were closely associated with TMPRSS2 and two types with IFITM3." (PMID 33061814, 2020). "Subsequently, IFITM3 overexpression in cancer tissues as compared to healthy adjacent tissue was confirmed in other cancers, including colonic, gastric, breast, prostate, lung, and liver." (PMID 33364194, 2020). "There is still much work to be done for confirming the mechanisms by which IFITM3 affects cancer progression, including progression of hematological malignancies." (PMID 33364194, 2020). "In this review, we discuss recent advances in IFITM3 biology, the regulatory pathways, and its function within cancer as part of immunity and maintaining stemness." (PMID 33364194, 2020). "Moving forward, we expect to see IFITM3 playing a larger role in human cancer and disease studies, as well as signaling pathways and personalized cancer treatments." (PMID 33364194, 2020). "The ability of IFITM3 to unite many signaling pathways has the potential to be applied in multitude of cancers." (PMID 33364194, 2020).